FGFBP3 (fibroblast growth factor binding protein 3)
Description:
Heparin-binding protein which binds to FGF2, prevents binding of FGF2 to heparin and probably inhibits immobilization of FGF2 on extracellular matrix glycosaminoglycans, allowing its release and subsequent activation of FGFR signaling which leads to increased vascular permeability.
Synonyms: FGF-BP3; C10orf13; MGC39320
Tractability: Antibody: UniProt places it where antibodies can reach, with high confidence; its Gene Ontology location is reachable by antibodies, with high confidence; UniProt predicts a signal peptide or a membrane-spanning region.
Gene: Protein-coding gene on chromosome 10 (91,906,584 to 91,909,486, reverse strand). Ensembl gene ENSG00000174721.
Subcellular location: Secreted
Pathways (Reactome):
Signal Transduction: FGFR2b ligand binding and activation
Gene Ontology:
Molecular function: fibroblast growth factor binding; heparin binding; growth factor binding
Biological process: positive regulation of fibroblast growth factor receptor signaling pathway; positive regulation of vascular permeability; cell-cell signaling
Cellular component: extracellular matrix; extracellular region
Genetic constraint (gnomAD): Loss-of-function variants: 5 observed, 5.84 expected, observed/expected ratio (o/e) 0.86, 90% interval 0.44 to 1.68. That is too few expected variants to judge how well the gene tolerates losing a copy. Missense variants: 429 observed, 307.67 expected, observed/expected ratio (o/e) 1.39, 90% interval 1.29 to 1.51. Synonymous variants: 215 observed, 144.76 expected, observed/expected ratio (o/e) 1.49, 90% interval 1.33 to 1.66.
Homologues: Orthologues: chimpanzee FGFBP3 (98% identical), macaque FGFBP3 (88% identical), dog FGFBP3 (74% identical), pig FGFBP3 (73% identical), mouse Fgfbp3 (58% identical), rat Fgfbp3 (56% identical), tropical clawed frog fgfbp3 (26% identical), zebrafish fgfbp3 (24% identical). Paralogues in human: FGFBP1 (17% identical), FGFBP2 (16% identical).
Diseases named in the same sentence as FGFBP3 in open-access papers:
FGFBP3 is named in the same sentence as 16 diseases in open-access papers, as found by Europe PMC text mining. Sharing a sentence is not in itself a finding about the gene and the disease. The quoted sentences say what the papers report.
Anxiety (2 papers, 2016 to 2018). Intense feelings of nervousness, tension, or panic often arise in response to interpersonal stresses. "As well as seeing altered expression in Fgf1 and Fgfr1, we also see a 46 % decrease in Fgfbp3, a gene that has been associated with the regulation of anxiety." (PMID 27295951, 2016).
breast carcinoma (2 papers, 2013 to 2020). "For ER+ breast cancer, the burden of rare SNPs in gene FGFBP3 was nominally globally associated (p = 6×10−7) although follow-up using exact logistic regression gave a larger p-value (1.0×10−4)." (PMID 23555315, 2013). "In breast cancer, the strongest associations included either SNPs in or gene burden scores for genes LDLRAD1, SLC19A1, FGFBP3, CASP5, MMAB, SLC16A6, and INS-IGF2." (PMID 23555315, 2013).
autism (1 paper, 2020). Persistent deficits in social interaction and communication and interaction as well as a markedly restricted repertoire of activity and interest as well as repetitive patterns of behavior. "Another interesting gene upregulated in KI and KO NSCs and downregulated in rescue cell lines was the autism candidate gene FGFBP3." (PMID 31820119, 2020).
cardiac hypertrophy (1 paper, 2024). "FGFBP3 and switch-associated protein 70 (SWAP70) may protect against weight gain and cardiac hypertrophy, respectively." (PMID 39190027, 2024).
diabetes (1 paper, 2020). "Noticeably, the injection of FGFBP3 has been patented as a treatment for diabetes, obesity, and nonalcoholic fatty liver disease." (PMID 32831068, 2020).
glioma (1 paper, 2022). A benign or malignant brain and spinal cord tumor that arises from glial cells (astrocytes, oligodendrocytes, ependymal cells). "In conclusion, FGFBP3, VAX2, and SHD were protective prognostic biomarkers against Macrophage M2 infiltration in low-grade glioma." (PMID 35432538, 2022).
melanoma (1 paper, 2021). A malignant, usually aggressive tumor composed of atypical, neoplastic melanocytes. "In summary, all patients affected with PDAC and melanoma in family 25-9-44 carried the DAB1, POLQ and FGFBP3 variants, whereas none of the healthy individuals carried all three variants." (PMID 34357098, 2021).
metabolic syndrome (1 paper, 2018). A cluster of metabolic risk factors for CARDIOVASCULAR DISEASES and TYPE 2 DIABETES MELLITUS. "Here, we report that FGFBP3 (BP3) modulates fat and glucose metabolism in mouse models of metabolic syndrome." (PMID 30374109, 2018).
pancreatic cancer (1 paper, 2021). "FGFBP expression is remarkably increased in PDAC compared with the normal pancreas and FGFBP3 was found to be induced early during pancreatic cancer carcinogenesis." (PMID 34357098, 2021).
pancreatic disease (1 paper, 2021). "A PCMS family carried pathogenic low-frequency variants in the DAB1, POLQ and FGFBP3 genes, with all three co-segregating with pancreatic disease." (PMID 34357098, 2021). "The present WGS, however, detected potentially pathogenic variants in the ATM, SUFU, DAB1, POLQ, MAP3K3, FGFBP3 and ACAD9 genes that co-segregated with pancreatic disease in single FPC families, and thus might predispose them to the disease." (PMID 34357098, 2021). "A new finding of the present study is that affected patients from one FPC family can carry identical germline variants in up to three different genes, e.g., DAB1, POLQ and FGFBP3 in family 25-9-44 or MAPK3 and ACAD9 in family 25-4-46, which segregate with pancreatic disease." (PMID 34357098, 2021).
spinal muscular atrophy (1 paper, 2025). A motor neuron disease that affect the muscles, and characterized by muscle weakness and atrophy resulting from progressive degeneration and irreversible loss of the anterior horn cells in the spinal cord (i.e., lower motor neurons) and the brain stem nuclei. "While females retained two of the signals in the main analysis (CHRNA5 and IREB2), males had a single new signal related to a gene involved in spinal muscular atrophy (FGFBP3)." (PMID 40074595, 2025).
tumor (4 papers, 2012 to 2025). "Noting that POU3F4 and FGFBP3 have been linked to a neural stem cell (NSC) identity, we compared DAOY cells in co-culture with the DAOY tumor spheroid sample for expression of NSC markers." (PMID 39896075, 2025). "Furthermore, overexpression of FGF12, FGF14, FGF17, FGFR1, FGFBP3 and IGFBPL1 genes was found in early tumor stage, while, overexpression of IGF1R, IGF2BP2 and INSRR was found in advanced tumor stages." (PMID 34061869, 2021).
FGFBP3 also shares sentences with these, for which no sentence is quoted: alcoholic liver diseases (1 paper); cancer (1); nonalcoholic fatty liver disease (1); Obesity (1).